ENSG00000287395 (novel transcript)
Gene: Long non-coding RNA gene on chromosome 1 (230,889,949 to 230,895,788, forward strand). Ensembl gene ENSG00000287395.
Gene Ontology:
Biological process: RNA processing
Cellular component: nucleolus